TMPO (thymopoietin)
Diseases named in the same sentence as TMPO in open-access papers (continued):
Sharing a sentence is not in itself a finding about the gene and the disease.
cancer (18 papers, 2009 to 2025). A tumor composed of atypical neoplastic, often pleomorphic cells that invade other tissues. "The Lem-D proteins, including Ankle2, Lemd2, TMPO, and Emerin, have been shown to be associated with many of the hallmarks of cancer." (PMID 38720803, 2024). "Furthermore, the carboxi-terminal domain of LAP2 is required to maintain the correct nuclear distribution of lamins A, B1 and B2 in cancer cells suggesting that TMPO mutations may destabilize lamin distribution in certain cell types." (PMID 34335680, 2021). "TMPO expression has previously been shown to correlate with the proliferative capacity in multiple cellular models, supporting a role for TMPO in unregulated cancer cell proliferation." (PMID 38720803, 2024). "The relationship between TMPO expression and cell proliferation has been investigated in several cancer types." (PMID 31602262, 2019). "Several studies have revealed the overexpression of TMPO in different cancer types, such as gastric, pancreatic, liver, and bile duct cancer." (PMID 31602262, 2019). "Although the expression of TMPO in cancer has been reported, understanding of the prognostic impact of TMPO on patients with cancer has been very limited." (PMID 31602262, 2019). "Thus, if the overexpression of TMPO comprises a common event in cancer, this event would be favored in CC due to the presence of HPV oncoproteins, and more specifically, due to the increasing TMPO-α, -β and -γ isoform levels." (PMID 40242184, 2025). "The mechanism by which TMPO is overexpressed in cancer is unclear." (PMID 31602262, 2019). "Recently, the role of TMPO in cancer biology has been reported." (PMID 27756319, 2016). "The potential EC-enriched candidate biomarkers included nicotinamide adenine dinucleotide NADH dehydrogenase (ubiquinone), 1 alpha subcomplex 5 (NDUFA5), peroxiredoxin 4 (PRDX4) and thymopoietin (TMPO), which were highly expressed in cancer cells compared to normal ones." (PMID 28250368, 2014). "Consequently, TMPO is involved in many aspects of cancer cell function." (PMID 38233377, 2024).
tumor (17 papers, 2009 to 2026). "Analysis of correlations between p-c-Fos and clinical parameters revealed that high p-c-Fos was significantly associated with tumor size and low expression of TMPO." (PMID 38233377, 2024). "Our findings build upon the existing knowledge of the roles of Lem-D proteins in tumor cells and demonstrate the role of several Lem-D proteins: Ankle2, TMPO, Emerin, and Lemd2 in TNBC growth and cell survival." (PMID 38720803, 2024). "Except for TMPO, this phenotype was demonstrated to be predominately tumor specific." (PMID 38720803, 2024). "For instance, tumor sample CCGA-UBC-034T contained an ecDNA with seven genes, including CDK4, DDIT3, GLI1, HMGA2, PTPN11, RFC5, and TMPO." (PMID 39267784, 2024). "Examples of those included PSPHL, TMPO, CRYBB2, and AMFR in the tumor epithelium and PSPHL, CXCL10 and CXCL11 in the tumor stroma." (PMID 19225562, 2009). "Consistently, siRNA-mediated depletion of TMPO has previously been shown to induce growth-inhibiting phenotypes, such as reduced proliferation and the induction of apoptosis, in non-cancerous dermal fibroblasts and tumor models." (PMID 38720803, 2024). "In addition, expression inhibition of TMPO, TOP2A, RFC3, GINS1, and CKS2 genes could prevent tumor growth and TRIB3 expression suppression would be a favorable target for anti−angiogenic therapy." (PMID 34249670, 2021). "Furthermore, expression inhibition of TMPO, TOP2A, RFC3, GINS1, and CKS2 genes could prevent tumor growth." (PMID 34249670, 2021).
infection (5 papers, 2017 to 2024). The state of being infected such as from the introduction of a foreign agent such as serum, vaccine, antigenic substance or organism. "This indicated that monochromatic blue light during incubation inhibited the development of thymus for the post-hatch chicks, which may affect production and release of thymopoietin and thymosin, and consequently reduce disease and infection resistant." (PMID 39123723, 2024).
TMPO also shares sentences with these, for which no sentence is quoted: colorectal cancer (5 papers); familial cardiomyopathies (2); Immunodeficiency (2); Obesity (2); triple-negative breast carcinoma (2); acquired immunodeficiency syndrome (1); Autoimmunity (1); brain tumor (1); cardiac tumors (1); channelopathies (1); epilepsy (1); HCMV infection (1); heart diseases (1); hepatocellular carcinoma (1); HIV-1 infection (1); inflammatory bowel disease (1); Lynch syndrome (1); malignant glioma (1); melanoma (1); neurological disease (1); Neuromyelitis Optica Spectrum Disorder (1); osteosarcoma (1); pancreatic ductal adenocarcinoma (1); thymic atrophy (1); thymoma (1); uterine cervix carcinoma (1).